PROK2 (prokineticin 2)
Diseases named in the same sentence as PROK2 in open-access papers (continued):
Sharing a sentence is not in itself a finding about the gene and the disease.
rheumatoid arthritis (4 papers, 2016 to 2023). A chronic, systemic autoimmune disorder characterized by inflammation in the synovial membranes and articular surfaces. "Among the prokineticin signaling components, Prok2 has been reported to play a role in autoimmune diseases, including psoriasis, rheumatoid arthritis (RA), and collagen-induced arthritis (CIA)." (PMID 38057865, 2023). "Prokineticin 2 (PK2) expression is upregulated in mice with collagen-induced arthritis (CIA), an animal model of rheumatoid arthritis." (PMID 27609223, 2016).
breast carcinoma (3 papers, 2020 to 2022). "PROK2-expressing neutrophils are involved in the 5-fluorouracil-induced aggravation of breast cancer metastasis to lung." (PMID 32887509, 2020). "PROK2 might be related to drug resistance of breast cancer and metastasis to lung." (PMID 32887509, 2020).
Cerebral ischemia (3 papers, 2018 to 2026). Restriction of arterial blood supply to the brain associated with insufficient oxygenation to support the metabolic requirements of the tissue. "In neurological contexts, miR‐141‐3p participates in regulating neural stem cell neurogenesis and modulates neuronal apoptosis by targeting PBX1 to regulate PROK2 transcription in cerebral ischemia models." (PMID 41523988, 2026). "Prokineticin 2 (Prok2) has also recently been identified as a deleterious mediator for cerebral ischemia." (PMID 30439964, 2018). "Conversely, a neuroprotective role for PROK2 has been also reported in cerebral ischemia." (PMID 33732160, 2021).
Cognitive impairment (3 papers, 2015 to 2017). Abnormal cognition is characterized by deficits in thinking, reasoning, or remembering. "A correlation between cognitive impairment in HD and thelevels of the peptide hormone prokineticin 2 (PROK2) involved in the regulationof circadian rhythms was revealed.Therefore, PROK2 is considered as one of the promising markers of HDprogression." (PMID 28740725, 2017). "Prokineticin 2 (PROK2) has been proposed to have a role in the circadian rhythms alterations that have been shown to correlate with cognitive impairment in HD." (PMID 26442283, 2015).
colitis (3 papers, 2016 to 2022). Inflammation of the colon. "PROK2 is elevated in colitis tissue, which, like appendicitis, is an inflammatory condition in the GI tract." (PMID 27417541, 2016).
lymph node metastasis (3 papers, 2018 to 2022). "Positive PROK2 expression in primary tumors was found in 222 of 436 (50.9%) human CRC specimens and was significantly associated with lymphatic invasion, lymph node metastasis, clinical stage, and postoperative liver recurrence rate." (PMID 30046389, 2018). "On the other hand, PROK2 expression was significantly correlated with lymphatic invasion and lymph node metastasis." (PMID 30046389, 2018). "PROK2 expression was positively correlated with the incidence of PC carcinoma (p = 0.015), but not correlated with lymph node metastasis or an advanced stage (p = 0.210 and p = 0.709, respectively)." (PMID 35626106, 2022).
myocardial infarction (3 papers, 2020 to 2022). Gross necrosis of the myocardium, as a result of interruption of the blood supply to the area, as in coronary thrombosis. "Thus, a non-peptide agonist specific for PKR1, called IS20, was developed to mimic the cardioprotective effects of PROK2 against heart failure developed by myocardial infarction and anthracyclines in mice." (PMID 34386529, 2021). "Expression of PROK2 and PKR1 levels are altered in patients with abdominal aortic rupture, during end-stage cardiac failure after acute myocardial infarction, and in adipose tissues from obese patients." (PMID 34386529, 2021).
Brain injuries (2 papers, 2021 to 2023). "Brain injuries trigger a cascade of pathophysiological processes that ultimately lead to cell death, and our data reveal a potentially important role for ProK2 during recovery from a TBI." (PMID 34223558, 2021).
cervical cancer (2 papers, 2015 to 2020). A primary or metastatic malignant neoplasm involving the cervix. "High expression of MMP15 is confirmed in the human cervical cancer, is significantly associated with the shorter overall survival rate (OS) and is correlated with PROK2 expression." (PMID 32887509, 2020). "Cervical cancer cells transfected with PROK2 shRNA had a significant decrease in the transcription and translation of MMP15." (PMID 32887509, 2020). "To investigate the effects of PROK2 on cell proliferation and cell cycle on HeLa cells, we infected cervical cells with PROK2 shRNA to generate PROK2 shRNA-stable cervical cancer cells." (PMID 32887509, 2020). "PROK2 knockdown in cervical cancer cells considerably suppressed the capacity in cellular migration, invasion, and MMP15 expression." (PMID 32887509, 2020). "In the present study, we observed that PROK2 is required for the migration and invasion of human cervical cancer cells." (PMID 32887509, 2020). "The capacity of migration and invasion in human HeLa cervical cancer cells were downregulated when PROK2 expression is silenced by shPROK2." (PMID 32887509, 2020). "The present study suggests that PROK2 acts a critical role in the progression of human cervical cancer." (PMID 32887509, 2020). "PROK2 knockdown by shRNA attenuated the capacity of migration and invasion in human HeLa cervical cancer cells." (PMID 32887509, 2020). "In this study, we first reported that PROK2 is high expressed in cervical cancer, particular in the advanced stages (III and IV)." (PMID 32887509, 2020). "In conclusion, our findings are the first to demonstrate the role of PROK2 as a novel and potential biomarker for clinical use, and reveal the oncogenic functions of PROK2 as therapeutic target for cervical cancer." (PMID 32887509, 2020). "PROK2 was expressed in higher amounts in human cervical cancer tissues compared with adjacent normal tissues." (PMID 32887509, 2020). "Cervical cancer patients with high PROK2 expression have a significant shorter OS rate and DFS rate." (PMID 32887509, 2020). "To investigate the potential role of PROK2 in cervical cancer, we analyzed PROK2 expression in human cervical cancer tissues." (PMID 32887509, 2020). "We further show that PROK2 is important factor for oncogenic migration and invasion in human cervical cancer cells." (PMID 32887509, 2020). "In conclusion, we demonstrated that PROK2 regulation of cell migration and invasion of human cervical cancer cells by targeting MMP15." (PMID 32887509, 2020). "The relation between MMP15 and PROK2 expressions have been further investigated in human cervical cancer." (PMID 32887509, 2020). "Cervical cancer patients with high PROK2 expression have a shorter overall survival rate (OS) and disease-free survival rate (DFS)." (PMID 32887509, 2020). "We further used the in vitro migration and invasion assay to identify the role of PROK2 in regulating cell migration and invasion of human cervical cancer cells." (PMID 32887509, 2020). "PROK2 could be considered as a potential prognostic biomarker and therapy target for human cervical cancer." (PMID 32887509, 2020). "Our results indicate that PROK2 is overexpressed in the human cervical cancer." (PMID 32887509, 2020). "PROK2 was highly expressed in cervical cancer tissue, particularly in patients at stage III." (PMID 32887509, 2020). "In future research will be focus on the antitumor effect and novel pathways of PKRA7 (PROK2 antagonist) in human cervical cancer, and it may be important implications for the development of molecular target drug against human cervical cancer." (PMID 32887509, 2020). "Inhibition of PROK2 might improve the treatment effect of cervical cancer." (PMID 32887509, 2020). "Change of MMP15 expression by PROK2 may contribute to cervical cancer metastasis." (PMID 32887509, 2020). "PROK2 might acts as a potential predictor and molecular target for cervical cancer therapy." (PMID 32887509, 2020).
cervical cancer (continued). "However, the biological function, underlying molecular mechanism and clinical significance of PROK2 in human cervical cancer has not been explored." (PMID 32887509, 2020). "Cervical cancer patients with MMP15 overexpression have a shorter OS; (v) PROK2-expressing vector reverses PROK2 shRNA-inhibited MMP15 expression, migration and invasion of cervical cancer cells." (PMID 32887509, 2020). "Our studies indicated that PROK2 is high expressed in the advanced stages (III and IV) of cervical cancer, and is positively correlated with poor survival of patients." (PMID 32887509, 2020). "However, the role of PROK2 in the development of cervical cancer remains unknown." (PMID 32887509, 2020). "We measured the effect of PROK2 on protein and mRNA expressions of MMP15 in human cervical cancer HeLa cells by using RT-qPCR and immunoblot assays." (PMID 32887509, 2020). "GEPIA was used to further confirm the high expression of PROK2 in patients with the advanced stages (III and IV) of human cervical cancer." (PMID 32887509, 2020). "Overexpression of PROK2 using PROK2 plasmid significantly reverses the function of knockdown PROK2, and further upregulates MMP15 expression, migration and invasion of human cervical cancer cells." (PMID 32887509, 2020). "PROK2 acts as a potential biomarker for predicting OS and DFS of cervical cancer patients." (PMID 32887509, 2020). "PROK2 was correlated with low OS and DFS in patients with cervical cancer." (PMID 32887509, 2020).
CHARGE syndrome (2 papers, 2013 to 2022). CHARGE syndrome is a multiple congenital anomaly syndrome characterized by the variable combination of multiple anomalies, mainly Coloboma; Choanal atresia/stenosis; Cranial nerve dysfunction; Characteristic ear anomalies (known as the major 4 C's). "These include the genes KAL1, FGFR1, FGF8 which encodes the ligand of FGFR1, PROKR2 and PROK2, NELF (nasal embryonic factor) and mutations in CHD7 associated with the CHARGE syndrome." (PMID 24204987, 2013). "Although CHD7 was originally considered to be the causative gene for CHARGE syndrome, subsequent research showed that CHD7 mutations can also be detected in KS patients lacking mutations in KAL1, FGFR1, PROK2, and PROKR2." (PMID 34231173, 2022).
congenital hypogonadotropic hypogonadism (2 papers, 2013 to 2022). Congenital hypogonadotropic hypogonadism (CHH) is a rare disorder of sexual maturation characterized by gonadotropin (Gn) deficiency with low sex steroid levels associated with low levels of follicle stimulating hormone (FSH) and luteinizing hormone (LH). "Interestingly, few patients who had monoallelic missense mutations both in PROK2 or PROKR2, and in other KS or normosmic congenital hypogonadotropic hypogonadism genes, raising the idea of oligogenism." (PMID 23596439, 2013).
depression (2 papers, 2021 to 2022). "PROK2 is linked to circadian clock regulation which in turn is associated with multiple mood disorders, such as depression, bipolar disorders, and seasonal affective disorder." (PMID 33833401, 2021). "Among these genes were SOCS3 (FDR = 0.0039) and PROK2 (FDR = 0.0028), which have previously both been linked to depression." (PMID 33833401, 2021). "Expression of PROK2 has never been linked to treatment response in depression before." (PMID 33833401, 2021).
glioma (2 papers, 2020 to 2023). A benign or malignant brain and spinal cord tumor that arises from glial cells (astrocytes, oligodendrocytes, ependymal cells). "A previous study demonstrated that PKRA7 is a PROK2 antagonist, which blocking the PROK2 expression, and consequently suppressing the tumorigenic and angiogenesis abilities of PROK2 and its downstream significantly pathways in glioma and pancreatic cells." (PMID 32887509, 2020). "MicroRNA-374a acts as tumor suppressor to inhibit cell proliferation, cell cycle progression, and cell invasion through targeting PROK2 in human glioma cells." (PMID 32887509, 2020).
hypogonadism (2 papers, 2007 to 2013). A disorder characterized by decreased function of the gonads. "The inactivation of PROK2 or PROKR2 lead to defective olfactory morphogenesis and hypogonadism in mice and humans." (PMID 23596439, 2013).
inflammatory bowel disease (2 papers, 2020 to 2024). A spectrum of small and large bowel inflammatory diseases of unknown etiology. "However, two had been previously proposed in adult inflammatory bowel diseases (IBD), namely, MMP9 and PROK2." (PMID 32411805, 2020).
Insulin resistance (2 papers, 2021 to 2025). Increased resistance towards insulin, that is, diminished effectiveness of insulin in reducing blood glucose levels. "Prok2 is a crucial neuropeptide component of the circadian clock that may link insulin resistance, cardiovascular disease, and AD." (PMID 40979532, 2025).
ischemia (2 papers, 2021 to 2023). A hypoperfusion of the BLOOD through an organ or tissue caused by a PATHOLOGIC CONSTRICTION or obstruction of its BLOOD VESSELS, or an absence of BLOOD CIRCULATION. "The induction of PROK2 expression in response to pathological insults, such as ischemia and stroke, contributes to inflammation and negatively affects the pathophysiological response." (PMID 37895111, 2023). "Inhibition of PROK2 signaling using receptor antagonists reduces inflammation and the infarct volume of ischemia, suggesting that it may serve as a potential therapeutic approach to mitigate the detrimental effects of ischemic stroke." (PMID 37895111, 2023).
Kawasaki disease (2 papers, 2023 to 2025). A rare inflammatory disease characterized by an acute febrile, systemic, self-limiting, medium-vessel vasculitis primarily affecting children. "Conversely, prokineticin 2 levels are reduced in conditions such as Kawasaki disease-a self-limiting vasculitis-and neonatal necrotizing enterocolitis, both of which involve systemic inflammation." (PMID 40708957, 2025).
male infertility (2 papers, 2022 to 2025). The inability of the male to effect fertilization of an ovum after a specified period of unprotected intercourse. "Most of the top 60 genes are poorly characterized, and several have been recently linked to human male infertility, including C2orf78, POTEJ, and PROK2." (PMID 41282076, 2025). "On the other hand, as a chemokine, PROK2 supported a pro-inflammatory environment, favoring male infertility in the experimental model." (PMID 36289651, 2022). "This narrative review aims to illustrate the state of the art regarding, in particular, the role of PROK2 in male infertility." (PMID 36289651, 2022). "The focus of the present review is to update the actual knowledge on the role of PROK2 and its receptor PROKR1 on male infertility, considering evidence gathered from pre-clinical and human studies." (PMID 36289651, 2022).
neuropathy (2 papers, 2015 to 2021). A disorder affecting the nervous system that manifests with pain, tingling, numbness, and/or muscle weakness. "In this regard, we have recently described the involvement of a newly discovered chemokine, the prokineticin 2 (PK2), in the development of BTZ-induced neuropathy." (PMID 34769347, 2021).
Obesity (2 papers, 2016 to 2021). Accumulation of substantial excess body fat. "Prokineticin 2 (PK2) has been shown to regulate food intake, fat production, and the inflammation process, which play vital roles in the pathogenesis of obesity." (PMID 33883996, 2021).
osteoporosis (2 papers, 2022 to 2025). A condition of reduced bone mass, with decreased cortical thickness and a decrease in the number and size of the trabeculae of cancellous bone (but normal chemical composition), resulting in increased fracture incidence. "In the GSE62402 dataset, related to osteoporosis, two differentially expressed mRNAs, Prokineticin 2 (PROK2) and Colony Stimulating Factor 3 (CSF3), were identified." (PMID 40153574, 2025). "The interaction of PROK2 and CSF3, core genes related to osteoporosis inflammation, plays an important role in the mechanism of osteoporosis in patients with Alzheimer's." (PMID 36203970, 2022).
Parkinson disease (2 papers, 2023 to 2025). A progressive degenerative disorder of the central nervous system characterized by loss of dopamine producing neurons in the substantia nigra and the presence of Lewy bodies in the substantia nigra and locus coeruleus. "For instance, one study indicates that prokineticin 2 is highly expressed in Parkinson’s disease patients and serves as a biomarker in indicating gut inflammation." (PMID 40708957, 2025). "Similar to a recent study reporting that the prokineticin 2 is highly expressed in the neurodegenerative disease patients (such as the Parkinson’s Disease)." (PMID 40708957, 2025). "For instance, prokineticin 2 is markedly upregulated in neurogenic regions of patients with early-stage Parkinson’s disease, suggesting a role in neuroinflammation or neurodegeneration." (PMID 40708957, 2025).
prostate carcinoma (2 papers, 2017 to 2020). A carcinoma that arises from epithelial cells of the prostate gland. "PROK2 could be involved in prostate carcinogenesis and could be useful for prostate cancer outcome evaluation, and as a target for prostate cancer treatment." (PMID 32887509, 2020).
varicocele (2 papers, 2021 to 2022). A condition characterized by the dilated tortuous veins of the spermatic cord with a marked left-sided predominance. "The authors revealed that the varicocele-induced oxidative stress increased the expression of the PROK2, leading to apoptosis of spermatocytes." (PMID 36289651, 2022). "PROK2 was recognized as a crucial biofactor for physiological functions, which was overexpressed after varicocele as well." (PMID 34055003, 2021). "Based on observations of this study, we proved that PROK2 overexpressed in the varicocele rat model and lycopene improved the hypoxia-induced testicular injury by inhibiting the expression of PROK2." (PMID 34055003, 2021). "The results showed both testicular secretion function and spermatogenic function were declined, as PROK2 was upregulated in varicocele rats." (PMID 34055003, 2021). "Lycopene improved the hypoxia-induced testicular injury by inhibiting the expression of PROK2 and decreasing levels of IL-1β and IL-2, which might show us a novel and promising treatment for varicocele testicular injury." (PMID 34055003, 2021). "So, we thought one reason of PROK2 overexpression was varicocele-induced hypoxia in testis." (PMID 34055003, 2021). "So, we made a hypothesis that a lower expression of PROK2 would ameliorate hypoxia-induced testicular injury in a varicocele rat model and improve spermatogenesis." (PMID 34055003, 2021). "In a recent study, researchers found that the expression of PROK2 increased in a varicocele rat, but they did not proceed with a further study for the effect of PROK2 and the mechanism was not continuously explored." (PMID 34055003, 2021).
aneurysm (1 paper, 2022). Bulging or ballooning in an area of an artery secondary to arterial wall weakening. "Genes with inflammatory and immune functions, including interleukin 8 (IL-8), prostaglandin-endoperoxidase synthase 2 (COX2), selectin E (SELE), and prokineticin 2 (PROK2), were confirmed to be overexpressed in aneurysm rupture lesions." (PMID 36482903, 2022).
cervical tumors (1 paper, 2020). "We performed IHC staining to measure PROK2 protein expression in paraffin-embedded tissue samples of human cervical tumors." (PMID 32887509, 2020).
choanal atresia (1 paper, 2012). Choanal atresia (CA) is a congenital anomaly of the posterior nasal airway characterized by the obstruction of one (unilateral) or both (bilateral) choanal aperture(s), with clinical manifestations ranging from acute respiratory distress to chronic nasal obstruction. "Developmental defects of GnRH neurons and the olfactory bulb are associated with hyposmia, rarely associated with the clinical phenotypes of synkinesia, cleft palate, ear anomalies, or choanal atresia, and may be due to mutations of KAL1, FGFR1/FGF8, PROKR2/PROK2, or CHD7." (PMID 22229029, 2012).